VIP (vasoactive intestinal peptide)
Diseases named in the same sentence as VIP in open-access papers (continued):
Sharing a sentence is not in itself a finding about the gene and the disease.
colitis (continued). "Thus, DNBS and DSS-induced colitis were more severe in VIP-KO than wild-type mice." (PMID 31861827, 2019). "Moreover, VIP is beneficial for the development and maintenance of a colonic epithelial barrier structure under physiological conditions and promoting epithelial repair and homeostasis during colitis." (PMID 31861827, 2019). "In addition to SP and VIP, mRNA for a number of peptides is increased in colon tissues from mice undergoing experimental colitis induced by oil of mustard (OM; allyl isothiocyanate), a direct stimulant of small nerve fibers and a potent, acute inflammatory irritant." (PMID 20615234, 2010). "In addition, glucagon-like peptide 2 (GLP-2), an important regulator of nutritional absorptive capacity with anti-inflammatory actions, reduces intestinal mucosal inflammation in TNBS-induced colitis in rats by activation of VIP neurons of the submucosal plexus." (PMID 20615234, 2010). "The study also explored the targeting relationship between miR-30c and VIP, and its potential impact on UC and DSS-induced colitis through VIP regulation." (PMID 38342939, 2024). "A model of TNBS-induced colitis in DPP4-/- mice showed higher serum levels of neuropeptide Y (NPY), vasoactive intestinal peptide (VIP) and IL-6, which are all substrates of DPP4, compared to C57BL/6 mice." (PMID 35309368, 2022). "The levels of VIP and IL-6 in the colon and brain tissues were also increased in DPP4-/- mice during the acute inflammation phase of colitis." (PMID 35309368, 2022). "Although these data suggest the protective role of VIP in intestinal inflammation, a contradicting report demonstrated that VIP exacerbated DSS‐induced colitis." (PMID 35593111, 2022). "Upregulation of intestinal mucosal MCs expressing VPAC1 in close proximity to VIP in inflammatory bowel disease (IBD) and murine colitis, suggests that communication between MCs and VIP is upregulated during IBD and mouse colitis." (PMID 33239034, 2020). "Vasoactive intestinal peptide (VIP) had therapeutic and prophylactic effects in TNBS-induced colitis, which was related to the down-regulation role of the IFN-γ level in splenic and lamina propria CD4+ T cells." (PMID 32153570, 2020). "The first report on the role of VIP as a therapeutic agent in IBD was published in 2003, in the TNBS colitis model." (PMID 31861827, 2019). "In a recent study, this strategy confirmed that VIP-SSM prevented and ameliorated severe inflammation related to DSS-induced colitis, in a murine model of inflammatory bowel disease." (PMID 31695683, 2019). "We have previously shown that GLP-2 treatment alters submucosal neuronal populations in vitro by increasing the proportion of VIP and neuronal NOS (nNOS) expression, and stimulates VIP immunopositivity in vivo in colitis models." (PMID 28738080, 2017). "VIP treatment has been shown to reduce the severity of 2,4,6-trinitrobenzene sulfonic acid (TNBS)-induced colitis and to protect IEC barrier integrity during Citrobacter rodentium-induced colitis." (PMID 25932952, 2015). "VPAC1, a receptor for vasoactive intestinal peptide (VIP), enhances DSS induced colitis through activation of PKA and increased MMP-9 expression, among other mediators." (PMID 25948887, 2015). "However, the role of VIP and its receptors during colitis remains unclear." (PMID 25932952, 2015). "In a model of TNBS-induced colitis, which closely parallels the immune activation in Crohn's disease, injection of tol-DCs treated with Vasoactive Intestinal Peptide (VIP) significantly ameliorated the clinical and histopathology severity of colitis in mice." (PMID 24319468, 2013). "Treatment with VIP after the onset of TNBS-induced colitis in mice reduces the clinical and histopathologic severity of colitis as well as Th1 cytokine levels." (PMID 20615234, 2010).
colitis (continued). "In our study, V9 was found to increase the serum levels of 5-HT, VIP, and SP in group M mice, and coincidentally, V9 was found to decrease the expression of SERT and reduce the recovery of 5-HT in the serum of colitis mice by Western blotting." (PMID 39926427, 2025). "We did not observe differences in the degradation of VIP by proteases in colonic samples from controls, acute colitis and post-colitis animals." (PMID 34639054, 2021). "However, opposing effects in several inflammatory/autoimmune models developed in VIP KO mice such as LPS-induced endotoxemia, TNBS- and DSS induced-colitis and experimental autoimmune encephalomyelitis (EAE), a model for multiple sclerosis, have been reported." (PMID 31695683, 2019). "Another study using the TNBS-induced colitis model reported that treatment with VIP did not modify the clinical and histological parameters." (PMID 31861827, 2019). "They characterized the healthy role of VIP and VIP-SSM in the DSS-induced colitis model." (PMID 31861827, 2019). "The same low dose of VIP (0.5 nmol/ mouse) was chosen for our murine study as VIP in higher doses (1 and 5 nmol/ mouse) failed to provide beneficial impact on C. rodentium infection induced colitis due to downregulation of receptors." (PMID 30252907, 2018). "In the C. rodentium induced colitis model prophylactic administration of VIP ameliorated the colitis-induced epithelial damage compared with non-treated controls, though only a single time point at mid infection was investigated." (PMID 30252907, 2018). "Even though VIP had beneficial effects on mitochondria and epithelial cells in the 5–10 day treatment regimen, there was no clear benefit on colitis or infection clearance overall." (PMID 30252907, 2018). "However, we unexpectedly found that VIP knockout (KO) mice developed ameliorated EAE and reduced inflammation in models of LPS-induced endotoxemia and chemically-induced colitis." (PMID 27357191, 2016). "Notably VIPKO mice also showed heightened susceptibility to DNBS and DSS-induced colitis, while treatment with VIP rescued the phenotype, protecting VIPKO mice against DSS-colitis." (PMID 25932952, 2015). "Moreover, using sterically stabilized micelles for VIP administration (VIP-SSM), it was observed that a single dose of VIP-SSM significantly improved histological score, alleviated diarrhoea, and decreased pro-inflammatory cytokines in mice with DSS-induced colitis." (PMID 34983592, 2022). "In animal models, it has been observed that vasoactive intestinal peptide (VIP), an immunomodulatory neuropeptide released in inflammatory conditions, can generate tolDCs that can restore tolerance in vivo in trinitrobenzene sulphonic acid (TNBS)-induced colitis." (PMID 34360736, 2021). "The absence of an increased trypsin-like cleavage in post-colitis samples is similar to the results with VIP and in both cases, it is probable that the enzymes responsible for an increased trypsin-like activity with fluorogenic substrates differ from the proteases that process PAR1, PAR4 and VIP." (PMID 34639054, 2021). "Evidence of increased expression of VIP following inflammation was found in inflammatory bowel disease (IBD), ulcerative colitis, Crohn’s disease, gastric ulcer, diabetes, dextran sodium sulphate-induced colitis in rats, guinea-pig TNBS colitis, Helicobacter pylori infection, and axotomy." (PMID 32245119, 2020). "Infection with C. rodentium produced features typical of colitis (tissue damage, goblet cell depletion, increased crypt length, alteration of crypt architecture, neutrophils present in lamina propria) at day 10 and 14 post infection (p<0.05), but no VIP treatment regimen ameliorated the colitis." (PMID 30252907, 2018). "Although colitis or bacterial burden was not decreased, we did find beneficial effects on the epithelial cells and their mitochondria using regimens that included VIP administration day 5–10, whereas late (day 10–14) VIP treatments appeared less effective." (PMID 30252907, 2018).
colitis (continued). "However, although there was a tendency to decreased pathogen density in contact with the epithelium and in the spleen, VIP treatment failed to alleviate colitis." (PMID 30252907, 2018). "However, VIP treatment failed to alleviate colitis although it tended to affect pathogen localization in vivo." (PMID 30252907, 2018). "Similarly, whether miR-30c KO mice or not, after DSS-induced colitis, we detected upregulation of VIP expression in the colon of mice." (PMID 38342939, 2024). "Therefore, thrombin and trypsin-3 could be responsible for an increased trypsin-like activity in colon from post-colitis animals measured with fluorogenic substrates, while no increased VIP degradation was observed." (PMID 34639054, 2021). "Cleavage of substance P, VIP and the PAR2-based peptide was not different in the acute or post-colitis animals compared to controls." (PMID 34639054, 2021). "The processing of Substance P, VIP and the unmasking of the TL-sequence of the PAR2-based peptide were not different between control, acute or post-colitis animals." (PMID 34639054, 2021). "It needs to be noted that the action of NPs produced typically in the upper GIT portions (e.g., CGRP, NT, SP, VIP), studied in different models of colitis or on non-transformed colonocytes, can have both pro-inflammatory (NT, NPY, SP) and anti-inflammatory (CGRP, VIP) effects." (PMID 32429087, 2020). "Although VIP showed very profound effects in this study, it should be noted that other studies could not confirm the beneficial effects of VIP in TNBS-induced colitis." (PMID 26635804, 2015). "Moreover, inhibition or genetic deletion of VIP does not exacerbate colitis, but rather induces resistance to both TNBS- and DSS-induced colitis." (PMID 26635804, 2015).
Constipation (35 papers, 2013 to 2026). Infrequent or difficult evacuation of feces. "Constipation caused by spleen deficiency can lead to a decrease in serum SP and an increase in VIP and CGRP." (PMID 40115071, 2025). "Spleen deficiency constipation is closely related to intestinal microbiota dysbiosis, decreased intestinal enzyme activities, and abnormal VIP and 5-HT levels." (PMID 39844840, 2024). "Plasma VIP level can be significantly increased in constipation patients, and gastric motility such as disturbance of gastric electric rhythm and slowing of gastric emptying rate can be significantly weakened." (PMID 40115071, 2025). "A similar finding was found in rats, which showed significantly lower levels of MTL and SP while significantly higher amounts of CGRP and VIP in the serum in a rat model receiving drug-induced constipation." (PMID 40807605, 2025). "Our results showed that MBSFL significantly improved intestinal transport in a mouse model of constipation induced by cotrimoxazole by modulating the levels of SP, VIP, 5-HT, and NO." (PMID 40724304, 2025). "MMF S2 alleviated constipation by regulating the abundance of Psychrobacter in intestinal contents in turn affecting the VIP level, while S3 by regulating the abundance of Candidatus_Arthromitus in turn affecting the 5-HT level." (PMID 39844840, 2024). "Our results demonstrated that the constipation group had significantly decreased levels of SP and 5-HT and significantly increased levels of VIP and NO compared the normal group." (PMID 37686774, 2023). "A rat model with constipation has been shown to have decreased expression of VIP levels in colon tissues." (PMID 35711274, 2022). "Studies have reported that GI hormones such as motilin (MTL), cholecystokinin (CCK), gastrin (Gas), and SP are significantly decreased while SS and VIP are increased in constipation-induced rats." (PMID 36145085, 2022). "For inhibitory neurotransmitters, the levels of VIP (233.81 ± 5.26 ng/L) and ET (198.98 ± 4.36 ng/L) in the serum of constipation mice were increased compared with normal mice (VIP 207.16 ± 6.12 ng/L, ET 167.87 ± 4.57 ng/L)." (PMID 36687730, 2022). "In our study, we found that probiotic compounds can enhance the abnormalities of SP, MTL, and GAS, and reduce the abnormalities of VIP, SS, and ET-1, thereby regulating gastrointestinal regulatory hormones and relieving constipation." (PMID 35163930, 2022). "Anthraquinones in Cassia seed can regulate the release of vasoactive intestinal polypeptide (VIP), increase the volume of intestinal contents, stimulate intestinal mucosa and increase intestinal peristalsis, thus treating constipation." (PMID 31379965, 2019). "Acupuncture and electroacupuncture have been reported to alter various neurotransmitters in both patients with functional gastrointestinal diseases and animal models of constipation, such as serotonin (5-HT), motilin, and vasoactive intestinal peptide (VIP)." (PMID 29853946, 2018). "Effect of various samples on serum MTL (motilin), Gas (gastrin), ET (endothelin), SS (somatostatin), AchE (acetylcholine enzyme), SP (substance P) and VIP (vasoactive intestinal peptide) levels in activated carbon-induced constipation model mice." (PMID 25464378, 2014). "The serum levels of MTL, Gas, ET, AChE, SP and VIP in patients with constipation are lower than those in healthy individuals while the SS levels are higher." (PMID 23935751, 2013). "Overall, this investigation revealed that AN and CAN interventions could improve the reduced serum levels of MTL, SP, VIP, and ACh, thus alleviating constipation." (PMID 39346640, 2024). "In a rat model of loperamide-induced constipation, probiotic administration increased the fecal water content and intestinal motility by modulating gastrointestinal peptides such as motilin, vasoactive intestinal peptide (VIP), and AQP3." (PMID 38612481, 2024).
Constipation (continued). "Furthermore, the expressions of aquaporins and vasoactive intestinal peptide, crucial for regulating water transport and intestinal motility, were altered in the light-induced constipation model." (PMID 38612481, 2024). "Besides, aloe played an important regulation in promoting intestinal motility sufficiency and the levels of neurotransmitters balance with 5-HT, SP, and VIP on constipation mice." (PMID 35571728, 2022). "A study on treatment with B. adolescentis, a probiotic, significantly increased levels of MTL, Gas, and SP but decreased levels of SS and VIP compared with constipation-induced rats, which stimulated peristalsis and transport of feces, thus attenuating constipation." (PMID 36145085, 2022). "Psychrobacter in the CS2 group was negatively correlated with VIP, it maybe play a laxative role by regulating the content of VIP which revealed that S2 alleviated constipation by regulating the abundance of Psychrobacter in intestinal contents in turn affecting the VIP level." (PMID 39844840, 2024). "In a study of adults with constipation, plasma levels of serum serotonin (5-HT), GAS, and vasoactive intestinal peptide (VIP) were reduced, and growth inhibitor levels increased in patients with constipation." (PMID 40807605, 2025). "The constipation group exhibited significantly diminished levels of MTL, SP, and Gas, along with marked elevations in SS, ET-1, and VIP, as compared to the normal control group." (PMID 39944653, 2025). "In this study, we found that QCT can downregulate the expressions of AQP3 mRNA and protein via VIP‐cAMP‐PKA‐AQP3 signaling pathway, which prevent the reabsorption of water in the lumen by blood vessels, thus improving constipation." (PMID 34136194, 2021). "Moreover, 72-SDC could also raise Ghrelin, ET-1, VIP and AchE serum levels in constipation mice." (PMID 30832248, 2019). "Studies have found that the levels of ET, SS and VIP in control groups were higher than those in normal and B. adolescentis treatment groups, which means that B. adolescentis influenced the level of GI hormones, an index that could reflect the status of constipation." (PMID 28230723, 2017). "Compared with patients with constipation, MTL, Gas, ET, AChE, SP and VIP levels in the serum of healthy individuals are higher whilst the levels of SS are lower." (PMID 25452815, 2015). "Research indicates that low-frequency EA stimulation can enhance bowel motility in constipation by improving colonic myoelectrical activity, reducing the immunoactivity of VIP (Vasoactive Intestinal Peptide), and enhancing the immunoactivity of SP (Substance P), thereby improving constipation." (PMID 39722820, 2024). "The results of this study show that, compared to the constipation group, mice treated with red pine seed direct-drinking oil exhibited increased serum SP levels, while VIP, NO, and ET-1 levels decreased, approaching those of the normal group." (PMID 39857348, 2024). "We measured some serum factors related to intestinal motility and found that diphenoxylate-induced constipation could reduce the expressions of 5-HT, MTL, and SP in serum and increase the expressions of ET and VIP." (PMID 36687730, 2022). "Levels of NO and VIP were higher (43.42 ± 47.70 μM/mL, 10.8 ± 0.4 pg/mL), and levels of MTL (58.10 ± 46.00 pg/mL) and SP (25.56 ± 3.52 pg/mL) were much lower in constipation group than those in NC group (25.70 ± 19.56 μM/mL; 9.70 ± 1.77 pg/mL; 123.20 ± 37.00 pg/mL; 48.13 ± 21.9 pg/mL)." (PMID 34711130, 2021). "The colon level of SP in mice with constipation was lower than those in healthy individuals (p = .006), while the VIP (p = .3352) and 5‐HT (p = .1654) levels were not changed." (PMID 32884719, 2020). "Therefore, the decrease of SP and VIP concentrations in the serum of rats suggested the occurrence of constipation in experimental group after non-isoflavones diet intervention." (PMID 30564225, 2018).